CD4 (CD4 molecule)
Diseases named in the same sentence as CD4 in open-access papers (continued):
Sharing a sentence is not in itself a finding about the gene and the disease.
infection (continued). "However, unlike naïve 2W1S-specific CD4 T cells, Ag-experienced memory 2W1S-specific CD4 T cells quickly recover numerically, as well as their ability to proliferate in response to a secondary infection." (PMID 32903436, 2020). "In contrast, survivors that have experienced mild infections develop prominent levels of virus-specific CD8 + T cell responses without detectable antibodies, indicating that efficient and rapid virus clearance may have occurred prior to CD4+ T cell responses and antibody-production." (PMID 32922406, 2020). "However it is known that CD4+ T cells in gut, which express high levels of α4β7, are preferentially targeted early in infection regardless of mode of transmission, and this may also explain the lack of association seen in this population of PWID." (PMID 33166790, 2020). "Furthermore, at 2 wk postinfection, the number of CD4+CD25+FoxP3+ Treg cells was significantly lower in the lungs of CSE−/− mice, which was reversed at 4 wk postinfection, suggesting control of the proinflammatory immune response in the CSE−/− mice after 4 wk of infection." (PMID 32139610, 2020). "HDACi (no cellular activation) pre-treatment reduced infection by 3-fold compared to resting CD4 T cells while PKCa-treated cells triggering intermediate or high activation levels had infection rates below or similar to resting CD4 T cells at 48 hpi, well below CD3/CD28-activated cells." (PMID 32196533, 2020). "However, strain biases in CD4 T cells could be due to overall abundance of memory cells that were established from or boosted by infections which are often subclinical in nature and not recorded by physicians or the subjects themselves." (PMID 32884842, 2020). "It is conceivable that once the infection is established and expansion of Salmonella-specific CD4+ T cells has occurred in the periphery, the immune response is established, and the contribution of RTEs is minimal, thus thymic removal has no measurable impact on infection outcomes." (PMID 32722409, 2020). "However, TCR engagement by anti-CD3/anti-CD28 stimulation was found to overcome this block and increase HIV infection of all CD4 T cell effector subsets to levels that directly correlated with their metabolic activity, not activation status at the time of infection." (PMID 33235814, 2020). "Interestingly we observed significantly higher numbers of CD4+ T cells in the spleen (p = 0.0272) and in the lungs (p = 0.0048) of infected ferrets, and a trend toward higher numbers of CD8+ T cells in the lungs, indicating a T cell response to H7N9 infection at a key site of infection." (PMID 33072098, 2020). "However, CD4+ T cell deficiency does not affect the effector CD8+ T cell responding against E. cuniculi infection, suggesting CD4+ T cell is not the sole activator of CD8+ T cell response and another reason is associated with the route of infection." (PMID 32670257, 2020). "Given that little is known about the initial infection, and the effect of HIV exposure on colorectal mucosal immune cells, we next studied the infection levels in primary mucosal immune cells to see if we could see connections to the immune profiles and effect on CD4+ and CD8+ T cells." (PMID 32876566, 2020). "Furthermore, the higher expression of PD-1 seen on CD4 but not CD8 subsets before infection might provide a stronger inhibitory signal that dampens CD4 T cell responses and necessitates a higher number of CD4 TEff cells." (PMID 31736943, 2019). "Local recruitment of cytolytic CD8+ T cells to the site of infection is critical for the elimination of infected cells and analysis of virus specific CD8+ T cells may provide critical information for the design of novel immunotherapies targeting HIV-infected CD4+ T cells." (PMID 30921340, 2019).
infection (continued). "In addition, HIV actively replicated in humanized NOG-EXL mice, and infection induced a decrease in the percentage of CD4+ T-cells, inversion of the CD4:CD8 ratio, and changes in some cell populations, such as monocytes and dendritic cells, that recapitulated those found in human natural infection." (PMID 30871027, 2019). "We think that this phenomenon of high TB incidence may be due to multiple factors which include inability to reach a CD4 count threshold of > 500 cells/mm3 despite long term ART, impaired restoration of TB specific immunity, low usage of IPT in our cohort and high rate of TB re-infection." (PMID 31409289, 2019). "Early events in mucosal transmission of HIV-1 can involve infection of myeloid dendritic cells (DCs) that capture virus and travel to draining lymph nodes, where they could transfer HIV-1 to CD4+ T–follicular helper cells and other CD4+ T-cell subsets known to harbor the virus." (PMID 31304185, 2019). "Unexpectedly, calcitriol treatment did not reduce the infection of CD4+ T cells from HESNs that could be explained by several reasons, including the differential modulation exerted by this hormone on the activation state of T cells from HESNs compared to non-exposed." (PMID 31550271, 2019). "Notably, quiescent CD4+ T cells, which are metabolically and transcriptionally silent, were originally thought to be refractory to HIV infection; however, evidence suggests that partially activated cells can support infection, especially with subsequent stimulation." (PMID 31552706, 2019). "Furthermore, a lower frequency of latently infected SCM and/or CM CD4+ T cells has been found in adult and pediatric nonprogressors, as well as in a cohort of patients treated soon after infection who exhibited controlled viremia after ART discontinuation (termed “post‐treatment HIV controllers”)." (PMID 31619550, 2019). "It will be of interest to determine whether HIV-1 trapped on CD4-negative cells via the interaction between envelope PtdSer and PtdSer-binding molecules can be transferred to neighboring CD4-positive cells and mediate trans-infection." (PMID 31638994, 2019). "Here we expand on these findings and show that CD4+ T cell-(Lckcre), as well as pan T cell-(iLckcre) specific IL-4Rα deficient mice, on a BALB/c background, unlike global IL-4Rα deficient mice, are also not adversely affected in terms of resistance to primary infection with L. donovani." (PMID 31475014, 2019). "Hence, fibroblasts from endometrium, cervix, foreskin, and intestines might enhance the infection of CD4+ T cells, among other mechanisms, by a trans-infection process, similar to DCs, without being infected." (PMID 30787929, 2019). "This phase is not infection dependent but occurs as a result of some sort of endocytosis-related mechanism resulting in the virus being taken up into an intracellular compartment, which the virus can then escape from when the DCs/LCs interact with CD4+ T cells (63, –, 66)." (PMID 31772057, 2019). "However, SAT or VAT do not differ significantly with regard to the level of HIV DNA in CD4 T cells – suggesting that environmental factors (e.g., low-grade inflammation, local microbial inflammation, and the viral load) do not drastically affect the level of infection of the CD4 T cell compartment." (PMID 31921023, 2019). "However, we did not observe any reduction in the HIV-1 trans-infection of CD4+ T cells." (PMID 31772057, 2019). "Similarly, T lymphocytes CD4+ may deal more damage, or at least become irrelevant, rather than hinder the progress of the infection." (PMID 31508399, 2019). "In fact, the infection and depletion of central memory CD4+ T cells (CD4+ TCM) (that are CCR5 negative and, in the absence of other stimuli, can only be infected by X4 viruses because they do express CXCR4) is hypothesized to contribute to the establishment of chronic immune activation." (PMID 30818365, 2019).
infection (continued). "However, although capable of efficiently restricting the fungal growth, mu MT mice did not survive the re-infection with Candida albicans, and this was concurrent with the failure to generate IL-10-producing dendritic cells and regulatory CD4(+)CD25(+) T cells." (PMID 31265468, 2019). "Although the correlation with Perf/GzmB expression may be prone to underestimation because of the prior release of cytotoxic molecules in vivo during ongoing infection, ∼5% of Perf/GzmB+ pMHCII tetramer+ CD4+ T cells lacked expression of Eomes, Hobit, and CX3CR1." (PMID 31308093, 2019). "Further, in the absence of IFN-I signaling, primary CD4+ T cells show improved expansion in response to infection with LCMV-Cl13, however it is not currently known whether the immunoregulatory properties of IFN-Is on CD4+ T helper cells is in a cell intrinsic or extrinsic fashion." (PMID 30791575, 2019). "However, the recruitment of other immune cell populations was similar between the two infections, possibly suggesting that the differences observed for inflammatory monocytes and CD4+ T cells did not result solely from the reduced bacterial burdens upon M. tuberculosis Δnrp infection." (PMID 30381350, 2018). "Indeed, the mean fluorescence intensity (MFI) of DCFDA was significantly increased in naïve, as well as memory CD4 T cells derived from HCV patients compared with HS, indicating that ROS generated during infection may play a role in DNA damage and cell apoptosis." (PMID 30185784, 2018). "Furthermore, the percentage of CD4+ T cells with a regulatory T cell (Treg) phenotype increases with aging and may be expected to impair responsiveness to immunizations or infection, although the existing data do not support such an impact." (PMID 29864157, 2018). "While we know that constitutive levels of IL-15 and IL-7 maintain homeostatic memory CD8 and CD4 T cell populations, the role of high levels of PRR-signaling such as that leading to type I IFN and other proinflammatory cytokines during active infection remains unclear." (PMID 29632538, 2018). "However, in our study the ART has been initiated late in the course of infection (CD4 < 350), it could be the reason for no improvement in the functionality of the iNKT cells even after suppressive ART for 12 months." (PMID 29881390, 2018). "Importantly, the detected transcriptional changes in the CD4+CD25+ T cell pool of B. bronchiseptica carriers were predominantly detected six, but not one week, following infection, and thereby pointed to carriage-associated mechanisms that were most likely of a regulatory manner." (PMID 30200513, 2018). "Thus, our data showing expansion of IL-10-producing effector CD4+ and CD8+ cells and Tregs, as well as by DCs, during the course of L. donovani infection could account for defective parasite killing by macrophages at later stages of infection." (PMID 29610255, 2018). "In addition, the kinetics of CD4+ T-cells in the genital tract of TLR3-/- mice during the early and middle stages of infection is similar to what is observed during C. muridarum infections in BALB/c and C57BL/6 mice showing that Th1 T-cells remain high after 3 weeks post-infection." (PMID 29624589, 2018). "However, in the alternative situation where CD4+ T cell deficient mice were infected with HSV-1, the infection could not be cleared." (PMID 29698393, 2018). "We found that the percentage of CD4+ T cells producing IFNγ and TNFα were significantly reduced in the groups receiving ART plus PH-797804 compared to ART alone, whether the treatment is started on week 1 (p = 0.005 for TNFα and p = 0.02 for IFNγ) or week 6 post-infection (p = 0.04 for TNFα)." (PMID 30161247, 2018). "Similarly, unactivated CD4+ T-cells sensitized with supernatants from infected MDMs treated with 25 ng/ml MIF showed a significant, albeit transient, increase in viral production at day 4 post-infection, compared to the uninfected condition, which was later downmodulated." (PMID 29997630, 2018).
infection (continued). "However, IFNγ-expression is strongly dependent on gGT activity, suggesting that CD4+ T cells might not be the major source of IFNγ during infection." (PMID 29057967, 2017). "As we identified no detectable infection driven expansion of vaccine-specific CD4+ T cell populations during the four day culture, we proceeded to investigate whether we could detect infection specific cytokine response (IFN-γ, IL-1β, IL-6, IL-10, IL-12p70 and TNF-α) in the culture supernatant." (PMID 28588268, 2017). "However, normal serum, immune serum depleted of IgG (protein A flowthrough), or Fab fragments prepared from immune IgG were unable to protect against infection, as these mice displayed a heightened, persisting infection that did not begin to resolve until after CD4+ T cell depletion had ended." (PMID 28739831, 2017). "Interestingly, when the HLN from the same study was examined, there was little evidence of expansion of the CD4 Foxp3 population with no significant changes in sheep with only goats showing a ~6% increase over baseline during the acute infection stages localized to the cortex." (PMID 28871261, 2017). "Non-cognate stimulation of CD4 T cells is less well understood, but Th1, Th2, and Th17 cells all have some capability to be stimulated upon encounter with a variety of cytokines, implying that this could be a common feature of the response to infection." (PMID 28817719, 2017). "Therefore, we intended to see whether CD4+ T cells generated in absence of B cells preserved their phenotype once transferred into a host that was ongoing a concomitant infection and was sufficient in B cells." (PMID 29209313, 2017). "Moreover, in accordance with the robust turnover in the naïve subset, the rapid decrease in naïve CD4+ T cell and naïve B cell numbers that was induced by SIVmac239 infection in old ChRM may have contributed to the gradual absence of their immune defense." (PMID 28232735, 2017). "Therefore, while cure and acquired resistance to VL correlated to the CD4+ Th1 and Th17 T-cell responses to F1, clinical VL outcomes, in L. (L.)infantum chagasi-infected individuals in contrast, correlated to CD8+ T-cell responses against F1, potentially involved in control of the early infection." (PMID 28747911, 2017). "Moreover, these fewer CD4+ and CD8+ T cells displayed reduced expression of activation markers such as CD69 and LFA1, consistent with data in spleen showing that mTORC1 inhibition of T cells on day 4 prevented T cell activation and trafficking to the brain later in infection." (PMID 29121917, 2017). "Finally, we show that the loss in mLN cellularity stems from defects in the mLN DC compartment, as transfer of Dectin-1+ DCs into KO mice restored fungal-specific CD4+ T-cell responses and mLN cellularity during infection, although it did not restore the effect on CD4+ T-cell apoptosis." (PMID 26349660, 2016). "A possible explanation for these findings is that CD160+ cells may be preferential targets for infection and depletion during ART, which would explain the strong negative association between the frequency of CD160+ CD4+ T cells and a putative marker of persistent viral replication." (PMID 27415008, 2016). "However, CD4+ T cell activation was absent from NOD.IFNAR1−/− mice until day 14 post infection." (PMID 27405244, 2016). "Therefore, while monitoring CD4 counts may add value in predicting PCP risk, this practice alone appears insufficient as the sole means to predict infection risk across immunosuppressed patients without HIV." (PMID 27721666, 2016). "Interestingly, although Dectin-1+ DCs could rescue the KO animals, they were not sufficient to fully restore CD4+ T-cell survival during infection, an observation that requires further exploration." (PMID 26349660, 2016).
infection (continued). "Interestingly, CD4-depleted IFN-γ−/− mice displayed an intermediate level of protective immunity to reinfection, characterized by the shedding of large numbers of infectious chlamydiae and an infection course of much longer duration compared to those seen with C57BL/6 controls." (PMID 27600502, 2016). "Interestingly, CD4 T cells needed to be activated prior to adoptive transfer, as high numbers of naïve CD4 cells could not afford protection against lethal Influenza A/Puerto Rico/8/34 (PR8) infection." (PMID 27014272, 2016). "Within the CD4 SP population, and beyond the increased basal death levels of Foxp3+ compared to Foxp3− cells, the latter population showed a significant increase in annexin V staining after infection; this not being the case among Foxp3+ cells in which such staining was visibly diminished." (PMID 26745276, 2016). "Additionally, whereas CD8 and CD4 T cell levels were similar in AT-SVF of uninfected healthy monkeys (ratio of 1.38, p = 0.18), the ratio of AT-SVF CD8 to CD4 T cells increased during infection and disease (1.51 during SHIV infection, and 1.59 during chronic enterocolitis, p < 0.05)." (PMID 27117277, 2016). "Thus, Vpr enhances the productive infection of non-activated CD4+ T cells." (PMID 27383627, 2016). "However, an overlooked challenge of using the QVOA is that it has been specifically “tuned” to CD4+ T cells, and may not be sensitive for detecting infection in cells that bear different HIV-1 replication dynamics than CD4+ T cells." (PMID 27998285, 2016). "Moreover, we assessed whether IL-27 controls IL-10 production by CD4+ T cells only in the spleen during infection or whether it exerts a dominant role in shaping the nonlymphoid CD4+ IL-10+ T cell response." (PMID 26459508, 2016). "The extensive contraction of the CD4+YFP+GFP+ T cell population, as well as their exhausted phenotype, after malaria infection indicated that the subset may not play a major role in shaping anamnestic immune responses during temporally separated rechallenge infections." (PMID 27630165, 2016). "In these correlation studies, the cooperative effects of CD4 and CD8 T cells cannot be adequately controlled for, yet both CD4 and CD8 T cells are specific for the internal, conserved IAV proteins suggesting that T cells may cooperate to diminish viral titers early in infection." (PMID 27014272, 2016). "In addition, since our analyses during the natural history of SIV-infection were performed in the early chronic phase of infection (day 58 p.i.), we cannot determine how the function of IL-17 and IL-22 producing CD4+ T-cells are affected in the early acute infection." (PMID 26829644, 2016). "Moreover, non-selective inhibitors of HDAC may induce HIV-1 expression from the HIV-1 reservoir in resting CD4(+) T cells, without new infection." (PMID 27931227, 2016). "CD4 downregulation prevents superinfection of cells, a condition that may induce premature cell death and also hypothetically ensures that infectious virions are not lost to redundant infection events." (PMID 26950141, 2016). "Since the recruitment of possible effector cells for antibody-mediated immunity was not impacted by CD4+ T cell depletion, we next assessed if CD4+ T cells were responsible for the activation of an effector cell population that functioned with antibody to resolve infection." (PMID 27600502, 2016). "However, our results, thus far, suggest that many of these CD4 T cells, specific for internal virion proteins, may not contribute positively to the antibody response following infection or vaccination." (PMID 26834750, 2016). "Because T cells specific for a subset of antigens within a herpesvirus-specific T-cell repertoire may selectively home to specific tissues, low frequencies of IE-1-specific CD4 T cells in peripheral blood may not exclude an important role of these T cells in control of infection." (PMID 26635812, 2015).